CLDN11 (claudin 11)
Diseases named in the same sentence as CLDN11 in open-access papers (continued):
Sharing a sentence is not in itself a finding about the gene and the disease.
melanoma (7 papers, 2015 to 2025). A malignant, usually aggressive tumor composed of atypical, neoplastic melanocytes. "In the literature, the CLDN (Claudin) gene family is known to be associated with tumor suppressor genes; for example, hypermethylation of the CLDN11 promoter occurs frequently in malignant melanoma of the skin, which may encode a novel melanoma-specific tumor suppressor gene." (PMID 31146393, 2019). "For instance, Gao and colleagues showed that the promoter hypermethylation of Claudin 11 (CLDN11) can be used to discriminate between CM and dysplastic nevi, thus representing a potential melanoma-specific epigenetic biomarker." (PMID 39358721, 2024). "Here we report significantly elevated methylation levels in metastatic MM compared to primary cancers, thus the frequency and level of CLDN11 methylation increases with the malignancy of melanoma." (PMID 26198249, 2015). "In primary melanoma a significantly higher frequency of CLDN11 methylation (49%; 19/39) was revealed (p = 0.001)." (PMID 26198249, 2015). "We analyzed the epigenetic inactivation of Claudin 11 (CLDN11) in malignant melanoma (MM) of the skin, including six melanoma cell lines, 39 primary melanoma, 41 metastases of MM and 52 nevus cell nevi (NCN)." (PMID 26198249, 2015). "Since most melanomas are driven by an activating mutation at codon 600 of BRAF, we also analyzed its mutational status and CLDN11 methylation in MM cell lines." (PMID 26198249, 2015). "To reveal the epigenetic status of CLDN11 in malignant melanoma (MM) cell lines, we have analyzed its aberrant methylation in buf1280, C8161, IGR1, MeWo, SKMEL13, SKMEL28, lung cancer (A549), cervix cancer (HeLa) and human fibroblast (HF) by COBRA." (PMID 26198249, 2015). "Claudin 11 (CLDN11) was recently identified as a member that is hypermethylated in human cancers including malignant melanoma (MM)." (PMID 26198249, 2015). "The aim of our study was to illuminate the epigenetic inactivation of CLDN11 in malignant melanomas (MM) in more detail." (PMID 26198249, 2015). "In summary, CLDN11 proved to be an epigenetically inactivated tumor related gene in melanomagenesis, and analysis of CLDN11 methylation level represents a potential tool for assisting in the discrimination between malignant melanoma and nevus cell nevi." (PMID 26198249, 2015). "It is tempting to speculate that CLDN11 methylation levels in primary MM contribute to differences in metastatic capacity of melanomas." (PMID 26198249, 2015). "Moreover, a significant increase in the methylation level of CLDN11 from primary melanomas to MM metastases was revealed (p = 0.003)." (PMID 26198249, 2015). "CLDN11 was unmethylated in normal human fibroblast (HF) and melanoma cell line SKMEL13." (PMID 26198249, 2015). "Thus it will be interesting to analyze the functional consequences of CLDN11 inactivation for invasiveness potential of melanomas in more detail." (PMID 26198249, 2015). "Recently, it has been suggested that Claudin 11 (CLDN11) could be a useful epigenetic biomarker for identifying malignant melanoma." (PMID 26198249, 2015). "In addition, it has been suggested that Claudin 11 (CLDN11) could be a useful epigenetic biomarker for identifying melanoma." (PMID 29100458, 2017). "Recently hypermethylation of Claudin 11 (CLDN11) has been reported in primary melanomas, however its epigenetic regulation was not analyzed in detail." (PMID 26198249, 2015).
colorectal cancer (6 papers, 2017 to 2025). A primary or metastatic malignant neoplasm that affects the colon or rectum. "Furthermore, claudin-11 inhibits cell migration and invasion in nasopharyngeal carcinoma, and hypermethylated claudin 11 is associated with metastasis of colorectal cancer." (PMID 36010553, 2022). "While DNA methylation in genes MDF1, SSTR2, CMTM3, TGFB2, and NDRG4 is a potential marker for the detection of colorectal cancer in the early stages of its development, hypermetylation in gene CLDN11 is associated with metastasis and poor prospect of patient survival with colorectal cancer." (PMID 32370233, 2020). "In addition, three genes were shown to be related with advanced colorectal cancer: CLDN11 (p = 0.007), and CLDN14 (p = 0.03) and CLDN23 (p = 0.021)." (PMID 35281827, 2022). "Our findings revealed that the mRNA expression levels of CLDN1, CLDN2, CLDN12, and CLDN14 were upregulated in colorectal cancer tissues relative to normal tissues in the Oncomine database, whereas CLDN3, CLDN5, CLDN7, CLDN8, CLDN11, CLDN15, and CLDN23 were downregulated, as previously reported." (PMID 35281827, 2022).
bladder cancer (5 papers, 2013 to 2023). "Forced expression of claudin-11 in bladder cancer cell lines blunted tumor invasion and increased cell matrix adhesion but increases tumor growth as well." (PMID 38188015, 2023). "First, CLDN11 is often inactivated in tumors; nevertheless, its re-expression decreases cell motility and invasiveness in gastric and bladder cancers, similar to the observations in this study." (PMID 29747653, 2018). "Claudin-11 decreases the invasiveness of bladder cancer cells, and knockdown of claudin-11 in glioma stem cells promotes cell proliferation, supporting its tumor suppressor function." (PMID 24009024, 2013). "Accordingly, the overexpression of claudin-11 would decreases the invasive potential of bladder cancer cells in vitro." (PMID 23919729, 2013).
colon cancer (5 papers, 2017 to 2025). "Claudin-11 hyper-methylation is linked to colon cancer progression and metastasis." (PMID 31887997, 2019). "We first confirmed that the expression levels of CLDN11 mRNA in the four colon cancer cell lines were significantly downregulated compared with those in normal colon tissue." (PMID 31500278, 2019). "An in vitro experiment also portrayed the aggrandized migration ability of human colonic cancer cells with hypermethylation of CLDN11." (PMID 29221203, 2017). "In vitro experiments showed debased migration ability of colonic cancer cells in accompany with the converted methylation of CLDN11 after colonic cancer cells treated with demethylation agent, 5-aza-2’-deoxycytidine." (PMID 29221203, 2017). "Our analysis revealed that the higher expression group of CLDN14 and CLDN11 are significantly correlated with the survival prognosis of colon cancer patients and the low expression group of CLDN23 is significantly correlated with shorter survival time of colon cancer patients." (PMID 37799140, 2023). "Our study showed that CLDN11/OSP is also regulated by miR-92a-3p in colon cancer." (PMID 31500278, 2019). "Then, we found that the expression of three deregulated claudins (CLDN11, CLDN14, and CLDN23) is significantly correlated with the shorter survival time of colon cancer patients as well as in the metadata of GSEA datasets." (PMID 37799140, 2023). "Exosome-mediated transfer of miR-92a from colon cancer cells to endothelial cells leads to angiogenesis induction through downregulation of Dickkopf-3 (DKK3) and claudin-11." (PMID 31887997, 2019).
male infertility (5 papers, 2018 to 2024). The inability of the male to effect fertilization of an ovum after a specified period of unprotected intercourse. "Apart from male infertility, defects in the CLDN-11 gene are implicated in several types of cancers and hearing loss." (PMID 39336792, 2024). "The Sertoli cells-specific knockout of Rnf20 causes male infertility through regulation of the cascade RNF20-H2BK120ub-CLDN11 during spermatogenesis in the mouse testis." (PMID 37024990, 2023). "Knockout of Rnf20 disrupts the prime factor in the regulatory cascade RNF20-H2BK120ub-CLDN11 during spermatogenesis and eventually causes male infertility." (PMID 37024990, 2023). "Loss of normal BTB function and decreased spermatogenesis have been found in undescended testes, suggesting that aberrant CLDN11 organization may induce undescended testes-associated male infertility." (PMID 36071829, 2022). "Furthermore, undescended testes exhibit a loss of normal BTB functionality and reduced spermatogenesis, implying that an abnormal organization of CLDN-11 may be a factor in male infertility linked to undescended testes." (PMID 39336792, 2024). "A deficiency in Necl2 results in male infertility in mice, characterized by abnormal BTB protein levels, including CLDN3, CLDN11, and Cx43." (PMID 39336792, 2024). "Phenotypes of male infertility in the Amh-Rnf20−/− mice are basically similar to those of the Cldn11 knockout mice." (PMID 37024990, 2023). "In addition, the impairment of spermatogenesis and male infertility were involved in an abnormal distribution of Cldn11 expression in the Sertoli cells." (PMID 37024990, 2023).
multiple sclerosis (5 papers, 2020 to 2024). A progressive autoimmune disorder affecting the central nervous system resulting in demyelination. "Multiple sclerosis is characterised by decreased levels of claudin-11 at the BBB of patients and of claudin-3 in a mouse model which exhibits lowered barrier tightness." (PMID 38891789, 2024). "The expression of CLDN11 is also reported to be significantly downregulated in the brain and spinal cord capillaries of patients with multiple sclerosis." (PMID 38584257, 2024). "Claudin-11 is also a well-established target antigen of the autoimmune condition multiple sclerosis." (PMID 37057071, 2023). "In another work about claudin-3 in multiple sclerosis, authors also found a normal tight and adherence junction expression profile like beta-catenin, claudin-11 and ZO-1 at the choroid plexus in claudin-3 null mice." (PMID 36261482, 2022).
COVID-19 (4 papers, 2020 to 2025). A disease caused by infection with severe acute respiratory syndrome coronavirus 2. "Tight junctions of the seminiferous tubules were also compromised in COVID-19 patients, with reduced levels of occludin and claudin-11." (PMID 36797789, 2023). "Suppression of tight junction genes such as CLDN11, CLDN16, and CLDN18 suggests impaired epithelial barrier integrity, potentially enhancing vascular permeability and pulmonary edema, as reported in COVID-19-related lung injury." (PMID 41200555, 2025).
Anxiety (3 papers, 2015 to 2024). Intense feelings of nervousness, tension, or panic often arise in response to interpersonal stresses. "CLDN11 knockout mice are characterized by impaired auditory processing and reduced anxiety/avoidance." (PMID 38534785, 2024). "However, our finding that expression of the myelination-related Cldn11 gene and anxiety correlated negatively in both the adult and neonatally fluoxetine-exposed rats does not support this." (PMID 26393488, 2015). "In the neonatally fluoxetine-exposed rats, Cldn11 expression also showed a negative correlation with anxiety-like behavior (OFC) in the OFT, despite the absence of significant differences between the treatment groups in the OFT and the expression analysis." (PMID 26393488, 2015). "Mice lacking Cldn11 exhibit central auditory deficits and reduced anxiety-like behavior." (PMID 36543780, 2022).
glioma (3 papers, 2013 to 2025). A benign or malignant brain and spinal cord tumor that arises from glial cells (astrocytes, oligodendrocytes, ependymal cells). "Pathway enrichment analysis demonstrated that specific CLDN genes, such as CLDN14 and CLDN11, regulated key pathways, including apoptosis, cell cycle, and DNA damage repair, suggesting their potential roles in glioma progression." (PMID 41425851, 2025). "Claudin-11 significantly inhibits the growth of glioma stem-like cells, and the expression of claudin-11 is regulated by miR-1275, indicating the importance of epigenetic mechanism in the regulation of glioma stem-like cells." (PMID 24009024, 2013).
hypomyelinating leukodystrophy (3 papers, 2023 to 2024). "Recently, stop-loss mutations in CLDN11 have been identified as a novel cause of hypomyelinating leukodystrophy (HLD22)." (PMID 38298375, 2023). "Also, a recent study reported that the stop-loss variants in CLDN11 cause hypomyelinating leukodystrophy in patients with HLD22, who exhibit early-onset spastic movement disorders, expressive speech disorders, and eye abnormalities." (PMID 37755363, 2023). "Recent findings identify de novo mutations in CLDN11, the gene encoding claudin-11, as a novel cause of hypomyelinating leukodystrophy (HLD), specifically leading to HLD22." (PMID 38298375, 2023). "Abnormal expression of the CLDN11 gene has also been reported in hypomyelinating leukodystrophy." (PMID 38534785, 2024).
ischemia (3 papers, 2018 to 2024). A hypoperfusion of the BLOOD through an organ or tissue caused by a PATHOLOGIC CONSTRICTION or obstruction of its BLOOD VESSELS, or an absence of BLOOD CIRCULATION. "Further evidence indicates that Kir4.1 deficits in NG2-glia potentially cause axonal myelin loss in ischemia through the association with oligodendrocyte-specific protein (OSP/Claudin-11), which unravels a potential therapeutic target in the treatment of ischemic stroke." (PMID 30271961, 2018).
lung carcinoma (3 papers, 2015 to 2025). "Furthermore, downregulation of PECAM1, VWF, CDH5, CLDN5, and CLDN11 was associated with poor overall survival and progression in lung cancer, which may emphasize a critical role of EndMT in these malignancies." (PMID 40083695, 2025). "These clusters include “connexin 43,” “myocardial infarction,” “prostate cancer,” “gene therapy,” “epithelial cells,” “cell adhesion,” “gene expression,” “bystander effect,” “lung cancer,” “endothelial cells,” “claudin-11,” and “stem cells”." (PMID 40416989, 2025).
lung squamous cell carcinoma (3 papers, 2019 to 2025). "Both CLDN1 and CLDN11 were highly expressed in human lung squamous cell carcinoma (SCC)." (PMID 31551535, 2019). "Interestingly, previous research has documented high CLDN11 expression in tumour cells from human lung squamous cell carcinoma 127, reinforcing the idea that the downregulation of CLDN11 identified in our analysis may predominantly arise from EndMT in endothelial cells." (PMID 40083695, 2025).
nasopharyngeal carcinoma (3 papers, 2018 to 2022). A carcinoma arising from the nasopharyngeal epithelium. "It was reported that inactivation of CLDN11 could promote cell migration in nasopharyngeal carcinoma." (PMID 32063918, 2019).
prostate carcinoma (3 papers, 2014 to 2025). A carcinoma that arises from epithelial cells of the prostate gland. "In summary, the present data identify the anoikis action of the novel lead compound DZ-50 in prostate cancer cells, by disrupting vital cellular interactions navigated by Claudin-11 (TJ) and talin (FAC), in the microenvironment." (PMID 24497940, 2014). "Our molecular analysis identified that the lead new quinazoline, DZ-50, disrupts tight junction formation in human prostate cancer cells by downregulating Claudin-11, a critical TJ protein, also contributing to the actin cytoskeleton." (PMID 24497940, 2014).
varicocele (3 papers, 2016 to 2024). A condition characterized by the dilated tortuous veins of the spermatic cord with a marked left-sided predominance. "Obviously, the changes in TJ protein (Occludin, Claudin-11, and ZO-1) expression caused by varicocele and MOP are the result of complicated biological events." (PMID 28090212, 2016). "For example, the downregulation of claudin-11 mRNA, an important protein for tight junction formation, was observed in varicocele-affected rat models." (PMID 38392299, 2024). "Animals lacking PPAR-α and TLR4 receptors showed reduced expression of claudin-11 and occludin when subjected to varicocele." (PMID 33668991, 2021). "As a result, we believe that TGF-β3 and TNF-α might be involved in the downregulation of TJ proteins, Occludin, Claudin-11, and ZO-1, and in the damage of the TJ structure that occurred in experimental varicocele." (PMID 28090212, 2016). "Overall, our results suggest that, in line with our previous study, PEA-um, via a TLR4-dependent pathway, selectively restores the expression of claudin-11 and occludin and reduces the expression of TGF-β3, p-ERK 1/2 and NLRP3 in varicocele mice." (PMID 33668991, 2021).
endometriosis (2 papers, 2020 to 2022). The growth of functional endometrial tissue in anatomic sites outside the uterine body. "Additionally, for claudin-2, a cytoplasmic shift in endometrioid endometrial carcinoma was reported, as was also the case for claudin-11 in endometriosis." (PMID 36428908, 2022). "Recently, we showed no decrease in claudin-7 and only subtle changes in the localization of claudin-11 in ectopic endometrium and suggested that only a partial EMT might be involved in the pathogenesis of endometriosis." (PMID 32140805, 2020). "However, as recently published by us, claudin-7 is not downregulated in endometriosis in contrast to subtle changes in localization of claudin-11." (PMID 32140805, 2020).
gastric tumors (2 papers, 2017 to 2021). "Hence, we can conclude that the hypermethylation can downregulate CLDN11 expression levels and further accelerate the development of gastric tumors." (PMID 34322159, 2021).
glioblastoma (2 papers, 2025). The most malignant astrocytic tumor (WHO grade IV). "Upregulation of TPPP3 has been linked to increased proliferation and invasion in glioblastoma cell lines, and CLDN11 has been reported to enhance invasiveness in small cell lung cancer." (PMID 41007824, 2025).
head and neck cancer (2 papers, 2021 to 2023). A primary or metastatic malignant neoplasm affecting the head and neck. "In head and neck cancer patients, claudin-11 prompts the formation of CTC clusters, which correlates with poor prognosis." (PMID 34354941, 2021). "In addition, CLDN11 was described to prompt the formation of circulating tumor cell clusters through the activation of a Snail–CLDN11 axis in head and neck cancers." (PMID 36672179, 2023). "The amplification frequencies of CLDN11 and CLDN16 are high in lung squamous, oesophageal, cervical, and head and neck cancers, but the expression levels are low in these cancer types." (PMID 34354941, 2021).
meningioma (2 papers, 2013 to 2023). A generally slow growing tumor attached to the dura mater. "Loss of claudin-11 may be considered to be putative indicators of recurrence and more aggressive behavior of meningiomas." (PMID 23919729, 2013). "Specifically, NF2 meningiomas expressed higher levels of arachnoid CLDN11 and pial LAMA2, while TRAF7 tumors overexpressed dural MGP and dural/arachnoid CRABP2 relative to NF2 tumors." (PMID 36937440, 2023).
metastatic cancer (2 papers, 2021 to 2022). A carcinoma which has spread from the original site of growth to another anatomic site. "Population-wide comparison between TT and LN single cells revealed that NOTCH2, NOTCH2NL, KIF5B, and ERBB4 are highly expressed in primary cancer, while CDK12, ERBB2, and CLDN11 are overexpressed in metastatic cancer." (PMID 33441952, 2021). "NOTCH2, NOTCH2NL, KIF5B, and ERBB4 are highly expressed in primary cancer, while ERBB2, CLDN11 and CDK12 are overexpressed in metastatic cancer." (PMID 33441952, 2021).